PARP1 (poly(ADP-ribose) polymerase 1)
Diseases named in the same sentence as PARP1 in open-access papers (continued):
Sharing a sentence is not in itself a finding about the gene and the disease.
lymph node metastasis (7 papers, 2013 to 2024). "In univariate analysis, the expression of PR, lymph node metastasis, PARP1, and NF-κB proteins was associated with distant metastasis of BC (P < 0.05)." (PMID 38388665, 2024). "PARP1 is associated with axillary lymph node metastasis, P=0.009." (PMID 35463096, 2022). "PARP1 expression was more frequent in the patients with higher tumor stage (P < 0.001), the presence of tumor invasion (P < 0.001), lymph node metastasis (P < 0.001), and venous invasion (P = 0.017)." (PMID 26540566, 2015). "With the status of distant metastasis of BC as the dependent variable, meaningful (P < 0.05) PR, number of lymph node metastases and PARP1 score in univariate analysis were taken as independent variables, and specific variables were assigned for Cox regression risk model analysis." (PMID 38388665, 2024).
myocardial ischemia (7 papers, 2013 to 2024). A disorder of cardiac function caused by insufficient blood flow to the muscle tissue of the heart. "The cytoprotective role of PARP-1 inhibition was shown earlier in pathophysiological conditions like myocardial ischemia/reperfusion injury/cardiomyocyte injury." (PMID 39294821, 2024). "It has been reported that over-activation of PARP1 led to apoptotic and necrotic cell death during Myocardial ischemia-reperfusion injury." (PMID 35178387, 2022). "And PARP1 silencing or specific inhibitors alleviated the promotion of FoxO3 activity upon starvation or myocardial ischemia, thus suppressing cardiac apoptosis and fibrosis." (PMID 30323296, 2018). "All these suggested that PARP1 inhibition protected against myocardial ischemia by blocking autophagy initiation." (PMID 30323296, 2018). "Poly-ADP ribosylation from PARP-1 and other sources of enzymatic poly(ARP-ribose) (PAR) synthesis is associated with cardiac damage following myocardial ischemia." (PMID 27547294, 2016). "Thus, we demonstrated that PARP1 is critically involved in the pathogenesis of myocardial ischemia injury through mediating cardiomyocyte autophagy." (PMID 30323296, 2018). "Furthermore, we demonstrated here inhibition of PARP1 could protect against cardiac ischemia injury by repressing autophagy via mediating FoxO3a signaling." (PMID 30323296, 2018). "Activation of PARP1 facilitates autophagy through poly(ADP-ribosyl)ation of FoxO3a, which impairs mitochondrial metabolism, promotes cardiomyocyte apoptosis, and exacerbates cardiac remolding induced by myocardial ischemia." (PMID 30323296, 2018).
nasopharyngeal carcinoma (7 papers, 2015 to 2024). A carcinoma arising from the nasopharyngeal epithelium. "It was previously reported that poly-(adenosine diphosphate-ribose) polymerase-1 (PARP-1) regulated ionizing radiation (IR)-induced autophagy in CNE-2 human nasopharyngeal carcinoma cells." (PMID 25872765, 2015). "Finally, poly(ADP-ribose) polymerase 1 (PARP-1) is overexpressed in nasopharyngeal carcinoma cells and tissues, and PARP inhibitors radiosensitise cells to IR whilst reducing tumour growth in combination with IR in xenograft models." (PMID 28415784, 2017). "This radiation-induced PARP-1 activation can also drive the migratory and invasive activity of CNE-2 nasopharyngeal carcinoma cells." (PMID 37351512, 2023). "In nasopharyngeal carcinoma cells, PARP-1 can activate autophagy through the AMPK/mTOR pathway such that interfering with PARP-1 or AMPK activity can suppress autophagic activity and increase CNE-2 nasopharyngeal carcinoma cell sensitivity to radiation treatment." (PMID 37351512, 2023).
psoriasis (7 papers, 2019 to 2025). An autoimmune condition characterized by red, well-delineated plaques with silvery scales that are usually on the extensor surfaces and scalp. "PARP1-mediated parthanatos has been implicated in psoriasis pathogenesis, wherein PARP1 promotes cutaneous inflammation through the induction of parthanatos-mediated cell death." (PMID 40332377, 2025). "Curiously, PARP-1 depletion enhanced the severity of psoriasis-associated inflammation." (PMID 31877876, 2019). "The results obtained in zebrafish prompted us to study the impact of inhibition of oxidative stress, NAMPT and PARP1, in organotypic 3D human psoriasis models." (PMID 34748530, 2021). "In imiquimod-induced psoriasis, PARP1 showed an anti-inflammatory action, and its PARP1−/− mice model in genetic deletion exacerbated symptoms by increasing the secretion of cytokines IL-6, IL-17, and IL-23." (PMID 37298466, 2023). "The known similarities and differences in the functions of PARP1 and PARP2 prompted us to assess the role of PARP2 in psoriasis." (PMID 37351597, 2023). "Transcriptomic data revealed strong increased mRNA levels of PARP1, AIFM1, and MIF in psoriasis lesional skin." (PMID 34748530, 2021). "Consistent with this, clinical data support the alteration of NAD+ and PAR metabolism in psoriasis, pointing to NAMPT, PARP1, and AIFM1 as novel therapeutic targets to treat skin inflammatory disorders." (PMID 34748530, 2021). "In conclusion, we report that hyperactivation of Parp1 in response to ROS-induced DNA damage, and fueled by NAMPT-derived NAD+, mediates inflammation through parthanatos cell death in preclinical zebrafish and human organotypic 3D skin models of psoriasis." (PMID 34748530, 2021). "Furthermore, the aberrant induction of NAMPT and PARP activity was observed in the lesional skin of psoriasis patients, supporting the role of these signaling pathways in psoriasis and pointing to NAMPT and PARP1 as potential novel therapeutic targets in treating skin inflammatory disorders." (PMID 37175698, 2023). "Genetic deletion or pharmacological inhibition of PARP1 was anti-inflammatory against Th2-mediated inflammation in contact hypersensitivity and irritant dermatitis reactions, while it was pro-inflammatory in the primarily Th17-mediated imiquimod (IMQ)–induced psoriasis model in mice." (PMID 37351597, 2023). "Specifically, we found that hyperactivation of PARP1 in response to DNA damage induced by reactive oxygen species, and fueled by NAMPT-derived NAD+, mediated inflammation through parthanatos cell death in zebrafish and human organotypic 3D skin models of psoriasis." (PMID 37175698, 2023). "We found that hyperactivation of PARP1 in response to reactive oxygen species (ROS)-induced DNA damage, and fueled by NAMPT-derived NAD+, mediates inflammation through parthanatos cell death in preclinical zebrafish and human organotypic 3D skin models of psoriasis." (PMID 34748530, 2021). "A study of chronic skin inflammation reveals that hyperactivation of PARP1 in response to ROS-induced DNA damage, fueled by NAMPT-derived NAD+, mediates skin inflammation via parthanatos cell death, identifying NAMPT, PARP1 and AIFM1 as novel therapeutic targets for psoriasis." (PMID 34748530, 2021).
schizophrenia (7 papers, 2019 to 2025). A major psychotic disorder characterized by abnormalities in the perception or expression of reality. "Parp1-deficient mice showed defective neurogenesis and maldevelopment of the brain, and manifested schizophrenia-like behavior." (PMID 37511534, 2023). "Our study suggests PARP-1 as a regulator of neurogenesis and a candidate gene associated with schizophrenia-related mental disorders." (PMID 31819047, 2019). "Therefore, more detailed characterization of the regional structural difference of the brain between WT and PARP-1 KO mice is needed to fully understand the neurodevelopmental defect associated with schizophrenia-like behaviors in the PARP-1 KO mice." (PMID 31819047, 2019). "In the current study we present evidence suggesting that PARP-1 regulates neurogenesis and its deficiency may result in schizophrenia-like behavioral deficits in mice." (PMID 31819047, 2019). "PARP-1-deficient mice exhibited reduced brain weight and schizophrenia-related behavioral deficits." (PMID 31819047, 2019). "Therefore, the altered neurodevelopment caused by PARP-1 deficiency may result in the dopaminergic hyperactivity, which produces, albeit partly, schizophrenia-like behaviors in PARP-1 KO mice." (PMID 31819047, 2019). "In the present study, we present evidence that PARP-1 regulates proliferation and differentiation of NSCs and its absence results in defective neurogenesis and behavioral deficits reminiscent of schizophrenia in mice." (PMID 31819047, 2019). "PARP-1 KO mice showed neurodevelopmental and behavioral deficits very similar with the phenotypes reported in the patients and the mouse models of schizophrenia." (PMID 31819047, 2019). "Among them, PARP1 and ZBTB16 were implicated in the pathogenesis of schizophrenia." (PMID 37511534, 2023). "Taken together, our results suggest that PARP-1 regulates neurogenesis during development and in adult and its absence may lead to the schizophrenia-like behavioral abnormality in mice." (PMID 31819047, 2019). "PARP-1 knock-out mice showed not only a high impact on NSC survival, DCX+ cells, and low neuronal differentiation that is associated with diminished social interaction but also with symptoms described as “schizophrenia-like behavioral deficits” that include hyperactivity and anxiety." (PMID 36407114, 2022). "The defective neurogenesis in the absence of PARP-1 during development and throughout the adulthood may be a cause of multiple behavioral abnormalities found in schizophrenia including anxiety, depression and deficits in memory, social interaction, and PPI." (PMID 31819047, 2019).
type 2 diabetes (7 papers, 2010 to 2025). "Increased NF-κB activation in type II diabetes mellitus has also been implicated in impaired vascular function, including myogenic tone, vascular reactivity, and inflammatory response through the detection of PARP-1, SP-1, and COX-2 activity." (PMID 40649025, 2025). "On the other hand, the role of ACSL5 in the context of type 2 diabetes pathogenesis still needs to be fully elucidated, including how it relates to PARP-1, before one can meaningfully embark on a similar study for that particular factor." (PMID 29392078, 2018).
atrial fibrillation (6 papers, 2019 to 2025). A disorder characterized by an electrocardiographic finding of a supraventricular arrhythmia characterized by the replacement of consistent P waves by rapid oscillations or fibrillatory waves that vary in size, shape and timing and are accompanied by an irregular ventricular response. "Their findings indicated that PARP1 inhibition, as well as NAD+ supplementation, may preserve atrial cardiomyocyte function in atrial fibrillation patients." (PMID 36407067, 2022).
chronic lymphocytic leukemia (6 papers, 2014 to 2025). "For instance, HSD17B8 has colocalization with lymphoid leukemia and chronic lymphocytic leukemia; RPN1 has colocalization with myeloproliferative diseases (excluding CML) and polycythaemia vera; and PARP1 has colocalization with myeloproliferative diseases (excluding CML) and polycythaemia vera." (PMID 41048997, 2025). "Besides, the elevated protein levels of cleaved-Parp1 and cleaved-Caspase3, and the decreased levels of B-cell CLL/lymphoma 2 in the stearic acid group were not rescued by the lncRNA TCONS_00230836 Smart Silencer." (PMID 34022799, 2021).
chronic obstructive pulmonary disease (6 papers, 2013 to 2020). A chronic and progressive lung disorder characterized by the loss of elasticity of the bronchial tree and the air sacs, destruction of the air sacs wall, thickening of the bronchial wall, and mucous accumulation in the bronchial tree. "More importantly, chronic obstructive pulmonary disease (COPD) patients exhibit higher PARP-1 activation in lymphocytes compared with healthy individuals, accompanied with higher levels of cytokines in plasma, suggesting the positive correlation of PARP-1 activity and chronic inflammation." (PMID 24278171, 2013). "Poly (ADP-ribose) polymerase (PARP)-1 is a nuclear enzyme involved in the pro-inflammatory signal transduction pathway of chronic obstructive pulmonary disease (COPD)." (PMID 24662074, 2014). "Studies on the role of poly(ADP-ribose)polymerase-1 (PARP-1) in acute lung injury (ALI) and chronic obstructive pulmonary disease (COPD)." (PMID 28974953, 2017). "We aimed to assess PARP-1 and PARP-2 expression and activity and DNA damage in tumors and non-tumor lungs from patients with/without chronic obstructive pulmonary disease (COPD)." (PMID 33187221, 2020).
depression (6 papers, 2019 to 2026). "PARP1 gene polymorphism has been found to be associated with depression, and increased PARP1 gene expression levels have been observed in individuals with depression." (PMID 38789433, 2024). "Furthermore, PARP-1 KO mice showed deficient social interaction and depression-like behavior as judged by the increased immobility in forced swim test." (PMID 31819047, 2019). "Of note, patients with major depressive disorders have elevated PARP1 levels." (PMID 30718786, 2019).
esophageal adenocarcinoma (6 papers, 2015 to 2025). A malignant tumor with glandular differentiation arising predominantly from Barrett mucosa in the lower third of the esophagus. "Chromatin-independent mechanisms of PARP1 mRNA abundance regulation were attributed to the action of miR-223 which targeted the PARP1 transcript in oesophageal adenocarcinoma cells." (PMID 28842672, 2017). "Efforts to increase diagnostic accuracy through FME have investigated several molecular markers such as EGFR, ErbB2 receptor tyrosine kinase 2, VEGF-A, fluorescent PARP1 inhibitor, chemokine receptor 4, heat shock protein 70, and c-MET for early esophageal adenocarcinoma detection." (PMID 39513952, 2025).
influenza (6 papers, 2015 to 2026). An acute viral infection of the respiratory tract, occurring in isolated cases, in epidemics, or in pandemics; it is caused by serologically different strains of viruses (influenzaviruses) designated A, B, and C, has a 3-day incubation period, and usually lasts for 3 to 10 days. "The host factor PARP1 (poly(ADP-ribose) polymerase 1) modulates chromatin remodeling and the transcription of human, swine, and avian influenza RdRP within human cells." (PMID 40278270, 2025). "In RdRP replicon (minigenome) assays and in authentic infection, PARP1 was required for optimal influenza polymerase activity, which canonically includes viral mRNA and vRNA and protein syntheses." (PMID 31015836, 2019). "CD40 has previously been shown to regulate immune response and promotes protection against the virus while PARP1 has been highlighted as a host factor that can regulate the polymerase activity of influenza." (PMID 31787983, 2019). "Moreover, treatment with recombinant CTSS protein enhanced influenza-induced PARP1 cleavage in a dose-dependent manner, further supporting a pro-apoptotic role for CTSS during infection." (PMID 41258714, 2026). "Further, peptides or inhibitors that target and block multiple caspases or PARP1 may be effective treatment targets for influenza infection." (PMID 37095508, 2023). "However, we found that PARP1's role in influenza infection appears to be more complex: inhibition of the PARylation enzymatic activity of PARP1 and PARP2 leads to increased influenza polymerase activity and greater replication of virus in human cells." (PMID 31015836, 2019). "Therefore, to further study IAV polymerase genotypes more comprehensively, we examined the requirement for PARP1 for activity of the polymerase for human, swine, and avian-derived influenza strains using an optimized influenza polymerase minigenome reporter assay." (PMID 31015836, 2019). "Cleaved-PARP1 increased dose-dependently, while p-MLKL and cleaved-GSDMD showed no consistent trends, indicating that apoptosis was the major pathway triggered by influenza infection in A549 cells." (PMID 41258714, 2026). "Conversely, treatment with recombinant CTSS protein exacerbated IAV-induced PARP1 cleavage and cytokine expression in A549 cells, indicating that CTSS acts as an amplifier of influenza-induced inflammatory and pathological injury process." (PMID 41258714, 2026). "Thus, PARP1 and other proteins in the virus-host interaction network are attractive targets for deeper study of host factors that regulate influenza virus infection and pathogenesis and development of new virus-host targeted molecules as antiviral therapy against severe influenza infection." (PMID 31015836, 2019). "The ribonucleotide synthesis enzyme inosine monophosphate dehydrogenase 2 (IMPDH2), a cellular factor that interacts with the PARP1 and PARP2 DDR proteome network, was also required for influenza NP synthesis." (PMID 31015836, 2019).
myeloid leukemia (6 papers, 2018 to 2025). A clonal proliferation of myeloid cells and their precursors in the bone marrow, peripheral blood, and spleen. "In the present study, using the CRISPR/Cas9 system and ssODN, we attempted to introduce the T315I mutation into three Ph+ myeloid leukemia cell lines that showed resistance to olaparib (a PARP1 inhibitor)." (PMID 29967475, 2018). "Next, icogenin, isolated from Dracaena draco, was tested on myeloid leukemia HL-60 cell line and induced nuclear changes, fragmentation of poly(ADP-ribose) polymerase-1, and led to apoptosis." (PMID 36500274, 2022). "PTTG1 knockdown decreased the cleavage of both caspase 3 and PARP1, which indicated that PTTG1 expression levels modulated the apoptotic effect induced by luteolin in human myeloid leukemia cells." (PMID 29649138, 2018). "Tatridin A is a germacranolide-type sesquiterpene lactone previously reported to induce apoptosis in human myeloid leukemia cell lines HL-60 and U937, mediated by early cytochrome c release, caspase-3 activation, and poly (ADP-ribose) polymerase-1 (PARP-1) cleavage." (PMID 41149747, 2025).
neuropathy (6 papers, 2013 to 2024). A disorder affecting the nervous system that manifests with pain, tingling, numbness, and/or muscle weakness. "Malignant transformations, tumor progression, the onset of some neuropathies and other disorders have been linked to misregulation of PARP-1 activity." (PMID 33273587, 2020). "It will also be interesting to determine whether PARP1's role in neuropathy/axonopathy, immune activation, and oligodendrogliopathy exhibits sex dimorphism in MS and animal models." (PMID 34935305, 2022). "Neuronal DNA damage might be expected following chemotherapy, resulting in extensive PARP-1 activation leading to neuronal dysfunction, aberrant somatosensory processing of the peripheral and/or central nervous system, and subsequent neuropathy." (PMID 23326593, 2013). "In contrast, knockout of PARP1, CD38, SARM1, and DBC1 protects mice against neuropathy induced via a high fat diet (HFD) or chemotherapy-induced neuropathy." (PMID 38256175, 2024). "The activation of PARP1 or CD 38 also promotes axonal degeneration, whereas the knockout of PARP1, CD38, SARM1, and DBC1 protect mice against high fat diet (HFD)-induced neuropathy or chemotherapy-induced neuropathy." (PMID 35563288, 2022). "In contrast, the knockout of PARP1, CD38, SARM1, and DBC1 protect mice against HFD-induced neuropathy or chemotherapy-induced neuropathy." (PMID 35563288, 2022). "Unlike immunomodulation, the direct demonstration of a role for PARP1 in neuropathy and axonopathy of MS and EAE is still lacking." (PMID 34935305, 2022).